Y_RNA (Y RNA )
Gene: Miscellaneous RNA gene on chromosome 7 (14,010,669 to 14,010,763, reverse strand). Ensembl gene ENSG00000252374.
Homologues: Orthologues: chimpanzee Y_RNA (98% identical), guinea pig Y_RNA (85% identical). Paralogues in human: RNY4 (85% identical), Y_RNA (85% identical), RNY4P10 (84% identical), RNY4P3 (84% identical), RNY4P7 (84% identical), RNY4P14 (83% identical), RNY4P19 (83% identical), RNY4P6 (83% identical), Y_RNA (83% identical), Y_RNA (82% identical), RNY4P13 (81% identical), RNY4P17 (81% identical), and 92 more.